MALAT1 (metastasis associated lung adenocarcinoma transcript 1)
Diseases named in the same sentence as MALAT1 in open-access papers (continued):
Sharing a sentence is not in itself a finding about the gene and the disease.
endometriosis (26 papers, 2017 to 2025). The growth of functional endometrial tissue in anatomic sites outside the uterine body. "Repression of lncRNA MALAT1 enhances the susceptibility of endometriosis to erastin-induced ferroptosis by regulating the miR-145-5p/MUC1 pathway." (PMID 40303288, 2025). "miR-200 family members block EMT by inhibiting ZEB1 and ZEB2 expression and by targeting metastasis associated lung adenocarcinoma transcript 1 (MALAT1) in endometriosis." (PMID 34449536, 2021). "In endometriosis, LncRNA MALAT1 has shown upregulation in ectopic endometrial tissue, contributing to the modulation of endometriosis pathogenesis." (PMID 41464345, 2025). "Discrepancies were also observed for MALAT1, which was increased in endometrial tissues but decreased in granulosa cells of patients with endometriosis." (PMID 41301870, 2025). "For instance, it was shown that MALAT‐1 contributes to hypoxia‐triggered protective autophagy, which is a process that promotes cell survival in endometriosis, reducing apoptosis." (PMID 36860157, 2023). "Nevertheless, MALAT‐1 role in endometrium homeostasis is still elusive, and studies highlighting its role in the development of endometriosis are emerging." (PMID 36860157, 2023). "Recent literature data suggest that the following lncRNAs are associated with endometriosis: UCA1, MALAT1, TC0101441, and H19." (PMID 36232884, 2022). "This assumption is reinforced by the observed effects of estradiol on expression of MALAT1 in the context of endometriosis." (PMID 35279108, 2022). "The study aimed to analyze the expression of four long non-coding RNA (lncRNA) genes, UCA1, MALAT1, TC0101441, and H19, in the context of the risk of developing endometriosis." (PMID 36232884, 2022). "In the present study, we found that MALAT1 was downregulated in erastin-induced ferroptosis in endometriosis." (PMID 35399101, 2022). "In our study, three of the four sequences we studied (UCA1, MALAT1, TC0101441) were found to be statistically insignificant from the point of view of endometriosis risk." (PMID 36232884, 2022). "In our study, we presented an analysis of the expression of UCA1, MALAT1, TC0101441, and H19lncRNAs in endometriosis patients compared to controls, to possibly correlate these lncRNAs with the risk of endometriosis." (PMID 36232884, 2022). "In contrast to endometriosis tissue where MALAT1 is overexpressed, in the granulosa cells of women with endometriosis MALAT1 expression is reduced." (PMID 34768856, 2021). "MALAT1 has been shown to induce EMT during endometriosis and metastasis in clear cell kidney carcinoma mouse models via the miR200/ZEB2 axis by acting as a sponge for the miR200 family." (PMID 34993023, 2021). "MALAT1 was identified as a sponge of miR-200c involved in the regulation of endometriosis stoma cell proliferation and migration by promoting ZEB1 and ZEB2 expression in women with the disease." (PMID 34768856, 2021). "Some authors showed that miR-200c, which is regulated by MALAT1, was downregulated in the endometrial tissue of patients with endometriosis." (PMID 34829891, 2021). "In this signaling cascade, expression of MALAT1 is regulated by the HIF1α transcription factor, known to be overexpressed in endometriosis lesions and to regulate multiple gene targets in response to hypoxia." (PMID 34768856, 2021). "It has been reported that long non‐coding RNA MALAT1 (lncRNA‐MALAT1) highly expressed in endometriosis and up‐regulated by hypoxia." (PMID 30324652, 2019). "The overlapping among lncRNAs involved in EC and Endometriosis showed that MALAT1 and H19 are shared across the two pathologies, even if, they show a different trend of expression." (PMID 30037059, 2018). "Recently, a paper demonstrated that the expression of MALAT1 is significantly increased during endometriosis." (PMID 30037059, 2018). "In this study, we demonstrated that expression of MALAT1 is significantly increased during endometriosis." (PMID 29116025, 2017).
endometriosis (continued). "We identified miR-200c as an EMT-suppressive miRNA in endometriosis that acts, at least in part, by downregulating the RNA level of MALAT1, which in turn functions as a ceRNA to upregulate ZEB1 and ZEB2 by sequestering miR-200c." (PMID 29116025, 2017). "In women with endometriosis, MALAT1 was discovered to function as a sponge for miR-200c." (PMID 41301870, 2025). "The MALAT1/miR-200c sponge could act as a novel target for the diagnosis and treatment of endometriosis." (PMID 35682695, 2022). "LncRNA MALAT1 is one of the studied lncRNAs in endometriosis." (PMID 35295989, 2022). "The synergistic effect of MALAT1 knockdown and erastin induction in ferroptosis may be a new therapeutic strategy for endometriosis." (PMID 35399101, 2022). "Compared with normal tissues, the expression of MALAT1 in endometriosis is upregulated." (PMID 35103065, 2022). "MALAT1 is another important lncRNA in endometriosis that cannot be increased." (PMID 34829891, 2021). "Most recently, it has been noted that E2-mediated MALAT1/miR200s axis may affect cell migration and invasion in endometriosis by regulating EMT, and hence may represent a potential therapeutic target." (PMID 34449536, 2021). "MALAT1 upregulation and miR200 downregulation have been observed in endometriosis." (PMID 34449536, 2021). "This implicates altered expression of MALAT1 in endometriosis-related infertility." (PMID 34768856, 2021). "In an example of indirect regulation of signaling pathway, knockdown of MALAT1 lncRNA in endometriosis cells leads to enhanced cell death, reduced migration and invasion associated with activation of Caspase-3, and downregulation of MMP-9 and the NFkB/iNOS signaling pathway." (PMID 34768856, 2021). "Moreover, the authors showed that miR-200c, which is regulated by MALAT1, was significantly down-regulated in endometrial samples from woman with endometriosis and they were significantly negatively correlated." (PMID 30037059, 2018). "Another lncRNA that is important in endometriosis is MALAT1." (PMID 30037059, 2018). "Overall, these findings suggest that the MALAT1/miR-200c sponge may represent a potential and novel therapeutic target for endometriosis." (PMID 29116025, 2017). "Studies have shown that an increase in MALAT1 under hypoxia can alleviate cell damage in ischemic brain injury and enhance cell survival in endometriosis, while MALAT1 may exacerbate hypoxic-reoxygenation damage in liver cells or hypoxia-induced lung dysfunction." (PMID 39199376, 2024). "Therefore, we hypothesized that MALAT1 may play an important role in erastin-induced ferroptosis in endometriosis." (PMID 35399101, 2022). "miR-200c by targeting MALAT1/ZEB1/ZEB2 could suppress endometriosis." (PMID 32850438, 2020). "The MALAT1/miR-200c sponge may be a potential therapeutic target for endometriosis." (PMID 29116025, 2017). "Therefore, miR-200c suppresses EMT by targeting MALAT1 in endometriosis." (PMID 29116025, 2017). "The MALAT1/miR-200c sponge significantly affects the proliferation and migration of endometriotic stromal cells, indicating that this sponge may be a novel target for the diagnosis and treatment of endometriosis." (PMID 29116025, 2017). "However, whether MALAT1 is involved in ferroptosis in endometriosis remains unclear." (PMID 35399101, 2022). "This study aimed to analyze the level of expression of four long non-coding RNA (UCA1, MALAT1, TC0101441, and H19) in endometriosis." (PMID 36232884, 2022). "Moreover, MALAT1-knockdown repressed GCs proliferation via the induction of the extracellular signal-regulated kinase (ERK)/mitogen-activated protein kinase (MAPK) pathway, suggesting that the MALAT1 dysfunction might have an adverse effect on the development of oocytes in endometriosis." (PMID 32503679, 2020). "Of note, the miR200/MALAT1 sponge mediating the EMT processes in endometriosis is complex and never exclusive." (PMID 29116025, 2017).
endometriosis (continued). "Although MALAT1 has been investigated in various human diseases, it has not been examined in endometriosis." (PMID 29116025, 2017).
neuroblastoma (26 papers, 2014 to 2025). Neuroblastoma (NB) is the most common solid, extracranial childhood tumor. "Our experiments revealed that TARDBP mRNA and MALAT1 RNA expression levels are similarly linked in the SH-SY5Y neuroblastoma cell line." (PMID 39837396, 2025). "For example, the metastasis-associated lung adenocarcinoma transcript (MALAT1) is upregulated in neuroblastoma cells under hypoxic conditions compared to normal conditions." (PMID 40104501, 2025). "The lncRNA MALAT1 is associated with hypoxia and angiogenesis in the context of neuroblastoma, with expression levels increasing under hypoxic conditions." (PMID 38891878, 2024). "MALAT1 has been proposed as a diagnostic or prognostic biomarker for neuroblastoma and, given its important impact on tumorigenesis, potential clinical applications cannot be ignored." (PMID 38891878, 2024). "In contrast, MALAT1 silencing leads to the reduction of vascularization, migration, invasion, and neurite growth and is associated with the arrest of neuroblastoma cell differentiation due to RAS/RAF/MEK/ERK pathway inhibition." (PMID 38891878, 2024). "RT-PCR and immunoblot analyses confirmed that MALAT1 suppression reduced FGF2 expression, and Enzyme-Linked Immunosorbent Assays revealed that transfection with MALAT1 siRNAs reduced FGF2 protein secretion from neuroblastoma cells." (PMID 26848616, 2016). "Disruption of MALAT1 expression partially rescues the cell death phenotype of MPP+-treated neuroblastoma cells, while ectopic overexpression of MALAT1 reverses this protective effect." (PMID 39837396, 2025). "Treatment with MPP+ in SH-SY5Y neuroblastoma cells significantly increases MALAT1 expression and induces cell death." (PMID 39837396, 2025). "A decrease in MALAT1 expression levels through GapmeR treatment did lead to cell death in SH-SY5Y neuroblastoma cells." (PMID 39837396, 2025). "The in vitro potency of ASOs with G-clamp modification was evaluated by measuring expression levels of Malat1 RNA in Neuro-2a mouse neuroblastoma cells 48 h after transfection with 0.4, 2, and 50 nM ASOs with and without G-clamp modification." (PMID 38978695, 2024). "MALAT1 expression profiling data from in vitro differentiation of Neuro-2a neuroblastoma cells showed that MALAT1 was significantly upregulated among other lncRNAs during differentiation." (PMID 35682796, 2022). "We performed a quantitative RNA-protein interaction screen using an in vitro RNA pulldown approach for Malat1 with nuclear extract from the murine NSC-34 neuroblastoma cell line." (PMID 32050583, 2020). "MYCN-mediated upregulation of Malat1 provides one mechanism in which its amplification can lead to increased metastasis in neuroblastoma patients." (PMID 31616462, 2019). "Consistently, Malat1 maintains survival and neurite outgrowth of Neuro-2a neuroblastoma cells probably via the ERK/MAPK signaling pathway." (PMID 29109677, 2017). "Taken together, our data suggest that up-regulation of MALAT1 expression in human neuroblastoma cells under hypoxic conditions increases FGF2 expression and promotes vasculature formation, and therefore plays an important role in tumor-driven angiogenesis." (PMID 26848616, 2016). "Here we show that the long noncoding RNA MALAT1 was upregulated in human neuroblastoma cell lines under hypoxic conditions." (PMID 26848616, 2016). "Using CHIP combined with gene chip technology, Koshimizu TA and his colleagues found that there were transcription factor CREB binding sites in the MALAT-1 promoter region in neuroblastoma cell lines." (PMID 26637808, 2016). "Microarray-based differential gene expression analysis showed that one of the genes most significantly down-regulated following MALAT1 suppression in human neuroblastoma cells under hypoxic conditions was fibroblast growth factor 2 (FGF2)." (PMID 26848616, 2016). "MALAT1 promotes tumor-driven angiogenesis by upregulating pro-angiogenic gene expression in neuroblastoma." (PMID 27458156, 2016).
neuroblastoma (continued). "Taken together, our data identify a novel pathway through which N-Myc causes neuroblastoma cell migration and invasion, and provide important evidence for further development of more potent JMJD1A/MALAT1 inhibitors for the prevention of tumor metastasis." (PMID 24742640, 2014). "The mechanism of cell death due to MALAT1 perturbation, and whether the effects of MALAT1 in neuroblastoma cells are dependent on TDP-43 function, remains unknown." (PMID 39837396, 2025). "MALAT1 is an lncRNA that contributes to the immune evasion of neuroblastoma cells." (PMID 38891878, 2024). "Additionally, we found that expression of the long noncoding RNA MALAT1 was significantly increased in senescent neuroblastoma cells, and that MALAT1 served as a sponge for microRNA (miR)-92a-3p to counteract miR-92a-3p-mediated repression of ADAM10 levels." (PMID 35309907, 2022). "For example, N-Myc oncoprotein up-regulates the histone demethylase JMJD1A which in turn up-regulates MALAT1 in human neuroblastoma cells, and that MALAT1 induces tumor-driven endothelial cell migration, invasion, and angiogenesis as well as tumor cell migration, invasion, and metastasis." (PMID 32174966, 2020). "Additionally, KDM3A and MALAT1 promote the migration and invasion of neuroblastoma cells, whereas the small-molecule pan-KDM inhibitor dimethyl N-oxalylglycine (DMOG) (2-OG cofactor inhibitor) inhibits such effects." (PMID 32354028, 2020). "MALAT1 also increases migration and invades neuroblastoma cells." (PMID 32099603, 2019). "It has been reported that MALAT1 is involved in the pathogenesis of LC and other human cancers, including liver, breast, colon, uterus, prostate, ovarian, and hematological malignancies and neuroblastoma." (PMID 31480503, 2019). "Conditioned media from neuroblastoma cells transfected with small interfering RNAs (siRNA) targeting MALAT1, compared with conditioned media from neuroblastoma cells transfected with control siRNAs, induced significantly less endothelial cell migration, invasion and vasculature formation." (PMID 26848616, 2016). "Importantly, knocking-down JMJD1A and MALAT1 gene expression significantly reduces neuroblastoma cell migration and invasion." (PMID 24742640, 2014). "The data suggest that MALAT1 induces neuroblastoma cell migration and invasion." (PMID 24742640, 2014). "Moreover, the small molecule JMJD1A inhibitor DMOG reduces MALAT1 expression and suppresses neuroblastoma cell migration and invasion." (PMID 24742640, 2014). "Finally, we evaluated SH-SY5Y cell viability to determine whether MALAT1 expression contributes to neuroblastoma cell death due to MPP+ toxicity." (PMID 39837396, 2025). "Therefore, MALAT-1 is a potential drug target and may facilitate the early diagnosis and establishment of a prognosis for neuroblastoma." (PMID 26637808, 2016). "MALAT1 promotes the upregulation of Fibroblast Growth Factor 2 (FGF2) mRNA and protein expression in neuroblastoma cells and enhances FGF2 secretion into the extracellular fluid." (PMID 40104501, 2025). "As a result, MYCN overexpression leads to MALAT1 overexpression, constituting another lncRNA-mediated mechanism by which MYCN contributes to neuroblastoma tumorigenesis." (PMID 38891878, 2024). "As a result, N-myc induces neuroblastoma cell migration and invasion by modulating KDM3A and MALAT1 levels, providing the evidence for the development of a KDM3A-selective inhibitor to block neuroblastoma metastasis." (PMID 32354028, 2020). "In human SK-N-SH neuroblastoma cells, the cAMP response element binding transcription factor (CREB) and its binding site on the MALAT1 promoter were required for the oxytocin-mediated MALAT1 overexpression." (PMID 30591689, 2018). "In a recent study where differentiated SH-SY5Y neuroblastoma cells were treated with BDNF and subjected to microarray studies, several lncRNAs including MALAT1/NEAT2 and MIAT/GOMAFU were found to differentially expressed." (PMID 29109677, 2017).
neuroblastoma (continued). "We evaluated the effects of MALAT1 and TDP-43 expression changes in neuroblastoma cells to determine whether these two molecules contribute to cell survival." (PMID 39837396, 2025). "In this study, we also investigated the consequences of MALAT1 and TDP-43 dysregulation in SH-SY5Y neuroblastoma cells in culture and in a model of neurodegeneration after drug treatment, to evaluate the importance of this RNA–protein interaction in contributing to human cell survival." (PMID 39837396, 2025). "We next repeated the TDP-43 IP-qPCR assays in the nuclear extracts of SH-SY5Y neuroblastoma cells treated with MPP+ in triplicate and found that TDP-43 binding to MALAT1 was significantly increased, while TDP-43 binding to the 3′ UTR of SLC1A5, CSNK1E, and HMGB2 mRNAs was significantly decreased." (PMID 39837396, 2025). "We first confirmed that heating increases NEAT1_2 extractability ~ 3.5-fold in WT neuroblastoma cells, whereas extractability of another lncRNA, MALAT1, is not affected." (PMID 30642400, 2019). "The current study shows that the small molecule JMJD1A inhibitor DMOG reduces MALAT1 gene expression, does not have an effect on neuroblastoma cell proliferation, but significantly reduces neuroblastoma cell migration and invasion." (PMID 24742640, 2014). "Moreover, JMJD1A and MALAT1 induced, while the small molecule JMJD1A inhibitor DMOG suppressed, neuroblastoma cell migration and invasion." (PMID 24742640, 2014). "Additionally, MALAT1 has been shown to have a significant positive relationship with Axl, a transmembrane receptor tyrosine kinase (RTK) that acts as an oncogene and is overexpressed in neuroblastoma." (PMID 40104501, 2025). "Therefore, we tested whether MALAT1 function contributes to cell survival in a model of neurodegeneration by evaluating the effects of alterations in MALAT1 and TDP-43 on cell viability and gene expression in SH-SY5Y neuroblastoma cells exposed to the neurotoxin 1-methyl-4-phenylpyridinium (MPP+)." (PMID 39837396, 2025).